TYK2 (tyrosine kinase 2)
Diseases named in the same sentence as TYK2 in open-access papers (continued):
Sharing a sentence is not in itself a finding about the gene and the disease.
psoriasis (continued). "Therefore, the biological functions of these hub genes may be highly consistent during the pathogenesis of psoriasis and TYK2/JAK1 treatment." (PMID 40560938, 2025). "We analyzed the genome-wide association study (GWAS) data and found that TYK2, caspase recruitment domain family member 14 (CARD14), NFK-BIA, TNFAIP3, TNIP1, IL-36RN, and other genetic polymorphisms in this pathway are associated with the pathogenesis of psoriasis." (PMID 29292715, 2017). "This positions TYK2 as a key regulator of both the IFN/Th1 and IL-23/Th17/IL-17 signaling pathways, which are critical in psoriasis and other immune-mediated diseases." (PMID 40095888, 2025). "Deucravacitinib, a selective TYK2 inhibitor, is currently the only JAK-family-targeting agent approved for moderate-to-severe psoriasis, further validating this pathway as a therapeutic target." (PMID 40506953, 2025). "Selective TYK2 inhibitors, such as deucravacitinib, also act on proximal IFN pathways and have been approved in psoriasis, with potential relevance for autoimmune conditions characterized by interferon signatures." (PMID 41153754, 2025). "However, the efficacy of topical TYK2 inhibitor in psoriasis remains unclear." (PMID 40038877, 2025). "To date, there have been very few reports of psoriasis with hematologic disorders such as MDS treated with deucravacitinib, and little discussion regarding the relationship between MDS and TYK2." (PMID 40519492, 2025). "Deucravacitinib, a selective oral tyrosine kinase 2 (TYK2) inhibitor, has demonstrated strong efficacy and safety in the treatment of psoriasis." (PMID 40519492, 2025). "One of the autoimmune diseases, psoriasis is largely an IL23‐driven disease, and thus inhibitors of TYK2 are effective therapy." (PMID 39835539, 2025). "In particular, TYK2, a member of the JAK family, plays a key role in IL-23 and type I interferon signaling, which are central to psoriasis pathogenesis." (PMID 40506953, 2025). "Psoriasis involves an early pDC/type I IFN burst in lesions that crosstalks with the IL-23/Th17 axis; selective TYK2 inhibition is now approved." (PMID 41153754, 2025). "These in vivo results, coupled with our in vitro findings, demonstrate that TYK2 inhibitor alleviates inflammation in KCs predominantly through the AKT‐SP1‐NGFR‐AP1 signalling pathway, thereby effectively reducing psoriasis‐like skin inflammation." (PMID 40038877, 2025). "Tyrosine kinase 2 (TYK2) is an intracellular mediator of cytokine signaling (e.g., interleukin‐23, interleukin‐12, Type I interferons); psoriasis pathogenesis involves interleukin‐23 and Type 1 interferon signaling." (PMID 40304108, 2025). "Emerging evidence suggests that tyrosine kinase 2 (TYK2) plays a critical role in the pathophysiology of both SLE and psoriasis." (PMID 40557031, 2025). "The tyrosine kinase 2 (TYK2) inhibitor deucravacitinib, approved for treating psoriasis, is currently being trialled in a phase III RCT for SLE after meeting its primary and key secondary endpoints in a phase II trial." (PMID 40473266, 2025). "Genome-wide association studies (GWAS) have identified numerous shared genetic regions between IBD and psoriasis, particularly highlighting key loci such as IL23R, IL12B, REL, and tyrosine kinase 2 (TYK2)." (PMID 39463646, 2024). "Other enzyme inhibitors targeting Janus Kinase (JAK) and tyrosine kinase 2 (TYK2) show a significant therapeutic effect in the clinical and preclinical evaluations of psoriasis." (PMID 38444844, 2024). "Current small molecule options for psoriasis include apremilast, a phosphodiesterase-4 (PDE4) inhibitor, and deucravacitinib, a recently approved tyrosine kinase 2 (TYK2) inhibitor." (PMID 38258121, 2024). "In 2022, a selective allosteric inhibitor targeting the TYK2 pseudokinase domain (deucravacitinib; BMS-986165) was approved by the U.S. Food and Drug Administration (FDA) for use in psoriasis." (PMID 38766166, 2024).
psoriasis (continued). "The Th22 inflammatory cytokine IL-22, a major player in psoriasis pathology, activates JAK proteins TYK2 and JAK1." (PMID 39337637, 2024). "Another cytokine IL-23, which is released by Th17 cells in the psoriasis immune response, activates JAK2 and tyrosine kinase 2 (TYK2)." (PMID 39337637, 2024). "Tyrosine kinase 2 (TYK2) is an intracellular mediator of cytokine signaling (e.g., interleukin [IL]‐23 and type I interferons) essential to psoriasis pathogenesis." (PMID 38268101, 2024). "Deucravacitinib, a type of TYK2 inhibitor, can potentially exhibit superior efficacy and safety compared to other JAK inhibitors in psoriasis treatment, possibly owing to its more specific and targeted mechanism of action in immune response." (PMID 37334353, 2023). "For example, IL-23, the crucial interleukin in the pathogenesis of psoriasis, transduces the signal by JAK2 and TYK2 and can be a target for the treatment of psoriasis." (PMID 34640327, 2021). "Tofacitinib, a TYK2 and JAK2 inhibitor developed for RA, is now making way to treatment options in other diseases such as, CD, UC, and psoriasis." (PMID 34108969, 2021). "These include the first-in-class inhibitor for JAK 1–3/TYK2 (PF-06263276) in chronic plaque psoriasis (NCT01981681), dual TYK2/JAK1 inhibitor (PF-06673518, pre-clinical) and Tyk2/Jak1 (PF-06700841) for ulcerative colitis, CD, and psoriasis in phase II." (PMID 33802091, 2021). "Interest focuses on the newly developed specific TYK2 inhibitor, BMS-986165, which has already completed a phase II trial for psoriasis and promises clinical efficacy in axSpA by preclinical data and translational research." (PMID 33193430, 2020). "The JAK1/JAK2/STAT1 and JAK1/TYK2/STAT3 pathways triggered by IFN-γ and IL-22, respectively, are aberrantly activated in psoriasis, as highlighted by the peculiar STAT1 and STAT3 signatures in psoriatic skin lesions." (PMID 30581877, 2018). "Our findings are supported by previous siRNA knockdown studies that showed targeted inhibition of JAK1 and TYK2 resulted in an almost complete elimination of IL-17, IL-22, and TGFβ signaling functions that could be harnessed therapeutically to treat patients with psoriasis pathogenesis and cancer." (PMID 29164058, 2017). "Seven of these have previously been reported for psoriasis (MHC, TRAF3IP2, IL12B, IL23R, IL23A-STAT2, TNIP1, TYK2)." (PMID 25651891, 2015). "When designing the topical formulation of the TYK2 inhibitor, we initially referred to the drug concentration of the pan‐JAK inhibitor tofacitinib (2% ointment) used in a phase 2a study for psoriasis, and also took into account the solubility of BMS‐986165 in DMSO." (PMID 40038877, 2025). "Further analyses on the function of DCs and CD4+ T cells revealed no significant alterations in PBMC and iLN, suggesting that the topical application of TYK2 inhibitor did not significantly affect the global immunity of psoriasis mice." (PMID 40038877, 2025). "TYK2 belongs to the Janus kinase (JAK) family and is involved in signaling pathways of cytokines, IL-12, IL-23, and type I interferons (IFNs), which play key roles in the pathogenesis of psoriasis." (PMID 40672022, 2025). "Tyrosine kinase 2 (TYK2) mediates the signaling pathways of proinflammatory cytokines such as interleukin (IL)-12, IL-23, and type I interferons (IFNs) and plays a pivotal role in the pathogenesis of psoriasis and various other immune-mediated diseases." (PMID 41096715, 2025). "Brepocitinib, a potent TYK2/JAK1 selective inhibitor, is being developed for psoriasis treatment." (PMID 39311381, 2024). "Deucravacitinib, an oral, selective, allosteric tyrosine kinase 2 inhibitor, is approved in Japan for adult patients with plaque (PP), generalized pustular (GPP), and erythrodermic (EP) psoriasis who have had an inadequate response to conventional systemic therapies." (PMID 38268101, 2024). "For example, TYK2 exerted protective effects on both autoimmune hypothyroidism (HPT) and psoriasis." (PMID 39009607, 2024).
psoriasis (continued). "Unlike the TYK2/JAK1-selective brepocitinib, TYK2-selective deucravacitinib did not demonstrate a significant association with dyslipidemia in the psoriasis trial, indicating the potential improvement in the safety profile of TYK2-selective targeting." (PMID 35056105, 2021). "In addition, there have been publications involving dual TYK2 and JAK1 catalytic inhibitors; SAR-20347, blocked psoriasis-like skin inflammation in mice and PF-06700841 (brepocitinib), was found to be protective against adjuvant-induced arthritis in rats." (PMID 34290741, 2021). "Drug targets identified by us that are already in use for the different IMIDs include drugs that target IL1B, IL6, TYK2, and JAK2.IL1B was present in the common cell-gene network of AS, CD, psoriasis, RA, and UC, indicating a similar mechanism between these diseases." (PMID 34108969, 2021). "TYK2 may play a protective role in the gut, which should be carefully considered in clinical trials, especially in patients with active enteritis; however, the recent TYK2 inhibitor trial in psoriasis did not report an increased risk of gut-related adverse events in comparison with placebo." (PMID 32149730, 2020). "The combined JAK1/TYK2 inhibitor, SAR-20347, demonstrated in vitro and in vivo concentration-dependent reduction of IL-12, IL-22, and IFNγ-mediated inflammation and tissue pathology in the imiquimod-induced psoriasis model." (PMID 31649667, 2019). "rs10782001 in FBXL19, rs1975974 in C17orf51, rs12720356 in TYK2, rs3792876 in SLC22A4, rs6908425 in CDKAL1, and rs13437088 in HLA-B/MICA have previously been associated with psoriasis, but not with type I psoriasis." (PMID 26613086, 2015). "Unlike JAK1, JAK2, and JAK3, TYK2 uniquely mediates intracellular signaling for key pro-inflammatory cytokines such as interleukin (IL)-12, IL-23, and type I interferons, which are central to the pathogenesis of psoriasis and other immune-mediated disorders." (PMID 40095888, 2025). "Notably, the population of IL17‐producing γδT cell, rather than Th17 cell, was significantly decreased in IMQ_986165 group, implying that the modulation of psoriasis outcomes by topical TYK2 inhibitor was not relied on suppressing Th17 cell function." (PMID 40038877, 2025). "Ustekinumab and IL-17 inhibitors are commonly used in psoriasis and have also been trialled for SLE.44 45 While the future for JAK and TYK2 inhibitors in SLE is currently unknown, this therapeutic strategy is of high interest, particularly for patients with comorbid psoriasis." (PMID 40473266, 2025). "Moreover, as a critical intracellular kinase within this pathway, tyrosine kinase 2 mediates IL-23 receptor signaling and downstream STAT3 activation, making it a promising therapeutic target for disrupting the IL-23/IL-17-driven inflammatory cascade in psoriasis." (PMID 40507893, 2025). "Unlike autoimmune diseases like psoriasis or alopecia areata, where only one JAK pathway is dysregulated, AD involves increased signaling through all four JAKs (JAK1, JAK2, JAK3, and TYK2)." (PMID 40151746, 2025). "TYK2 (tyrosine-protein kinase 2) is a non-receptor protein kinase that belongs to the JAK family and plays a crucial role in various diseases, including psoriasis, inflammatory bowel disease, and systemic lupus erythematosus." (PMID 39056736, 2024). "We noted that the PsA study index SNP is not always highly correlated with the reported psoriasis index SNP; notable examples include IL23R, TYK2 and NOS2A loci (r2<0.2)." (PMID 25651891, 2015). "Some of the hub genes in the pre/post-treatment (TYK2/JAK1) cohort were also identified by GSE14905 and GSE6710 at opposite expression levels as key genes, although GSE14905 and GSE6710 were not included in any pre/post-treatment psoriasis samples." (PMID 40560938, 2025).
psoriasis (continued). "Brepocitinib (formerly known as PF-06700841) is not a selective TYK2 inhibitor (rather a potent TYK2/JAK1 inhibitor), has shown good efficacy in phase II trials in psoriasis with few minor adverse effects, except thrombocytopenia and decreased reticulocyte count." (PMID 35265634, 2022). "Additionally, PPS may target signaling pathways involved in psoriasis, such as NF-κB, janus kinase/signal transducer and activator of transcription (JAK-STAT) and non-receptor tyrosine-protein Kinase (TYK2) pathways, MAPK pathway, and phosphoinositide 3-kinase/Akt (PI3K-AKT) pathway." (PMID 41226468, 2025).
autoimmune disease (79 papers, 2010 to 2026). A disorder resulting from loss of function or tissue destruction of an organ or multiple organs, arising from humoral or cellular immune responses of the individual to their own tissue constituents. "We show that rs34536443 (TYK2:p.Pro1104Ala), allele C which confers protection from different autoimmune disorders has been associated with several immunophenotypes." (PMID 39835539, 2025). "Polymorphisms in tyrosine protein-kinase 2 (TYK2) are associated with a reduced risk of several autoimmune diseases, including T1D, ulcerative colitis, and rheumatoid arthritis." (PMID 40335415, 2025). "Research indicates that the A allele of the rs2304256 polymorphism in the TYK2 gene reduces the function of the tyrosine kinase, potentially decreasing the risk of developing autoimmune diseases." (PMID 40066463, 2025). "Although the therapeutic potential of inhibiting TYK2 has been used in multiple autoimmune diseases, its potential in mitigating hypothyroidism risk remains largely unexplored." (PMID 41238958, 2025). "One such variant, TYK2:p.Pro1104Ala is associated with a lowered risk of several autoimmune disorders, and we have analysed its effects on immune cell levels." (PMID 39835539, 2025). "In agreement with the protection from autoimmunity provided by the TYK2:p.Pro1104Ala loss‐of‐function variant, selective TYK2 inhibition has been intensively explored for the treatment of autoimmune diseases and several inhibitors have been developed." (PMID 39835539, 2025). "The TYK2:p.Pro1104Ala (rs34536443) hypomorph variant has been associated with protection against numerous autoimmune disorders." (PMID 39835539, 2025). "In support of this, a recent study reported that the loss-of-function variant rs34536443 in TYK2 was associated with a lower risk of autoimmune disease including T1D23." (PMID 38351043, 2024). "Protective TYK2 genetic variants have been identified in autoimmune diseases, but their relevance in other pathologies such as hematopoietic malignancies is still uncertain." (PMID 38683377, 2024). "JAK2 and TYK2 are members of the JAK family that are linked to multiple cytokine receptor signaling pathways in the pathogenesis of autoimmune disorders." (PMID 38674328, 2024). "TYK2 loss-of-function variants have been described as protective in the outcome of autoimmune diseases)." (PMID 38683377, 2024). "Twelve associations of TYK2 gene expression with 6 autoimmune diseases in 8 tissues were identified in colocalization analysis (PP>80%)." (PMID 36842216, 2023). "Four studies evaluated the association between rs34536443 (g.10352442G>C) SNP and SLE, according to a meta-analysis involving 34 studies on the association of TYK2 polymorphisms with autoimmune disease." (PMID 37813633, 2023). "PheWAS-MR found that genetically-proxied TYK2 inhibition was associated with lower risk of a wide range of autoimmune diseases." (PMID 36842216, 2023). "It is suggested that the TYK2 gene is associated with susceptibility to inflammatory and autoimmune disorders." (PMID 37896870, 2023). "Previous studies have shown that the P1104A coding variant in the TYK2 gene has protective effects against a variety of autoimmune diseases." (PMID 37845748, 2023). "Our MR-PheWAS analysis confirmed the inverse associations between genetically proxied TYK2 inhibition and various autoimmune diseases." (PMID 36842216, 2023). "The observed associations of TYK2 with other autoimmune diseases, including hypothyroidism, systemic lupus erythematosus and rheumatoid arthritis, should help inform future clinical study design." (PMID 36842216, 2023). "Rare biallelic variants in TYK2 predispose to infection by intracellular bacteria or viruses, while at the same time, common TYK2 variants are associated with inflammatory and autoimmune disease." (PMID 37780853, 2023). "Contrastingly, the allele C of rs34536443 in the TYK2 gene protects against several autoimmune diseases, including SLE." (PMID 37813633, 2023).